STAT3 (signal transducer and activator of transcription 3)
Diseases named in the same sentence as STAT3 in open-access papers (continued):
Sharing a sentence is not in itself a finding about the gene and the disease.
urothelial carcinoma (8 papers, 2011 to 2025). A malignant neoplasm derived from the transitional epithelium of the urinary tract (urinary bladder, ureter, urethra, or renal pelvis). "For instance, activation of STAT3 in a mouse model of urothelial carcinoma was associated with expansion of KRT14high cells." (PMID 32326336, 2020). "For these reasons, we speculated that STAT3 expression might be associated with some molecular subtypes of urothelial carcinoma with worse prognosis such as basal-like type." (PMID 30091994, 2018). "The mean score of STAT3 expression was significantly higher in high grade urothelial carcinoma compared to low grade one (p<0.05)." (PMID 32102537, 2020). "Present study shows the relation between STAT3 expression parameters and tumor grade of urothelial carcinoma (UC)." (PMID 32102537, 2020). "In our current study we have demonstrated that urothelial carcinomas with papillary patterns showed lower parameters of STAT3 expression compared to the non-papillary variant, with significant differences for STAT3 intensity (p<0.05), percent (p<0.01) and score (p<0.01)." (PMID 32102537, 2020). "Consistent with a role for FEME in EGFR signaling, the stable silencing of Endophilin increases phosphorylation of AKT, GSK3β, SFK and STAT3 after EGF stimulation, mimicking the signaling pattern in urothelial carcinoma." (PMID 32589750, 2020). "Deregulation of STAT3 and PI3K/AKT pathways has been shown to play an important role in the development of urothelial carcinoma and correlates with tumor progression." (PMID 21408190, 2011). "Urothelial carcinomas with papillary patterns showed lower parameters of CDK4 and STAT3 expression compared to the non-papillary variant, with significant differences." (PMID 32102537, 2020).
allergic asthma (7 papers, 2014 to 2025). A asthma with a basis in a pathological type I hypersensitivity reaction. "Our RT-qPCR results showed that Lif, Jak1, and Stat3 transcription increased in lung tissues from mice with allergic asthma and decreased after emu-miR-10a-5p intervention." (PMID 40496853, 2025). "Supporting this idea, there is a study that states that local inhibition of the STAT-3/STAT-5/SOCS3 dependent feedback loop has been shown to suppress experimental allergic asthma." (PMID 24637581, 2014). "α-Asarone inhibited the phosphorylation level of STAT3, thus inhibiting mast cell activation, inflammatory cell infiltration, and the release of IL-5 and IL-13 in lung tissue, and finally effectively alleviating allergic asthma." (PMID 39444792, 2024). "Previous studies have indicated that within the lungs of mice with allergic asthma, DCs can activate the JAK/STAT3 signaling pathway by secreting IL-6, thereby promoting the differentiation and activation of Th2 and Th17 cells." (PMID 39078462, 2024). "The STAT3/SOCS3 and mitogen activated-protein kinase (MAPK) pathways can mediate allergic asthma." (PMID 40005151, 2025).
alopecia (7 papers, 2016 to 2025). Hair loss usually from the scalp. "Contrary to the alopecia-inducing effects of the earlier hub genes, STAT3, HIF1A, and MAPK3 are reported to counteract hair loss." (PMID 39056691, 2024). "The STAT3 GOF mutation patient received treatment with the anti-IL6R monoclonal antibody tocilizumab and achieved a stable condition with less alopecia, normal blood glucose levels and fewer infections." (PMID 32944025, 2020). "Given that STAT3 is known to play a role in regulating the hair cycle, its suppression might contribute to alopecia observed in some patients." (PMID 41464561, 2025). "Since JAK/Signal transducer and activator of transcription-3 (STAT3) pathway plays a critical role in mediating the activation of CD8+ NKG2D+ T cells, the inhibition of JAK appears as a plausible target for developing a therapy for hair loss." (PMID 30208587, 2018). "Additionally, numerous signaling pathways, including the stimulatory pathways, such as the Wnt/β-catenin, STAT3, and Shh pathways, as well as the inhibitory pathways including Dkk-1, BMP4, and Dickkorpf-related protein are implicated in the treatment of alopecia." (PMID 34099599, 2021).
amyloid (7 papers, 2019 to 2025). "To determine whether this potential regulatory role of STAT3 in BACE1 and γ-secretase expression underlies the observed impact of STAT3 inhibition on Aβ levels and amyloid pathogenesis, we examined BACE1 activity, levels of γ-secretase and soluble APPβ." (PMID 34911575, 2021). "Taken together, our in vitro and in vivo results suggest that another potential mechanism by which STAT3 inhibition attenuates amyloid pathogenesis and its associated neurovascular deficits is by reducing Aβ-induced oxidative stress production and its pathologic impact on LRP-1 expression." (PMID 34911575, 2021). "When combined with results from the in vitro study by Liu and colleagues, our in vivo results suggest one mechanism by which STAT3 inhibition attenuates amyloid pathogenesis and its associated neurovascular deficits is by attenuating APP processing through inhibition of BACE1 activity." (PMID 34911575, 2021). "STAT3-specific inhibition in a mouse model of amyloidosis improved cognitive function, functional connectivity and increased cerebral blood flow." (PMID 38811690, 2024). "Third, we identified two molecular mechanisms by which STAT3 inhibition may directly impact parenchymal and vascular amyloid pathogenesis—reduction in BACE1 activity and restoration of brain levels of LRP-1." (PMID 34911575, 2021). "While the beneficial effects of drugs that non-specifically inhibit STAT3 have been reported in transgenic mouse models of amyloidosis, direct evidence that STAT3-specific pharmacologic inhibitor attenuates amyloid deposition and ameliorates amyloid-induced neurovascular dysfunction is lacking." (PMID 34911575, 2021). "When applied to AD and CAA, these data raise the intriguing possibility that STAT3-mediated production of ROS could contribute to amyloid pathogenesis and amyloid-induced neurovascular deficits." (PMID 34911575, 2021). "Several studies have linked the JAK/STAT pathway to amyloidosis and AD, and our molecular docking results showed that GS-Rd can interact directly with JAK2 and STAT3, suggesting that GS-Rd may exert anti-AD activity by regulating Aβ deposition through the modulation of the JAK/STAT pathway." (PMID 36588689, 2022). "First, we demonstrate that broad STAT3 inhibition (i.e. beyond astrocyte-specific gene deletion) provides robust protection not only against neuritic plaques and neuroinflammation, but also provides marked protection against vascular amyloid in the form of CAA and cerebrovascular dysfunction." (PMID 34911575, 2021). "First, broad inhibition of STAT3 via administration of the STAT3-specific inhibitor, LLL-12, markedly improved multiple histological, biochemical, physiological, and functional endpoints in a mouse model of amyloidosis." (PMID 34911575, 2021). "Importantly, neither of these studies examined the potential role of STAT3 in the profound cerebrovascular deficits found in mouse models of amyloidosis and AD patients." (PMID 34911575, 2021). "To explore additional mechanisms by which STAT3 inhibition positively impacts amyloid deposition, we further examined whether LLL-12 treatment reduces amyloid-induced oxidative stress and its impact on LRP-1—a key molecule involved with Aβ clearance across the blood–brain barrier (BBB)." (PMID 34911575, 2021).
atrial fibrillation (7 papers, 2014 to 2024). A disorder characterized by an electrocardiographic finding of a supraventricular arrhythmia characterized by the replacement of consistent P waves by rapid oscillations or fibrillatory waves that vary in size, shape and timing and are accompanied by an irregular ventricular response. "STAT1 and STAT3, which we also associate with arrhythmogenic right ventricular dysplasia, were recently found to be elevated in mice with sustained atrial fibrillation." (PMID 24516403, 2014). "MiR-4798-3p was indicated to modulate TLR4 and STAT3, and it was closely linked with the prevalence of atrial fibrillation in males and also could regulate genes involved in the pathogenesis of AF." (PMID 37422588, 2023). "Studies have also shown that FGF-23 induces atrial fibrosis in patients with atrial fibrillation by increasing reactive oxygen species (ROS) production and subsequently activating signal transducer and activator of transcription 3 (STAT3) and SMAD3 signaling." (PMID 34497820, 2021). "TGF-β transgenic mice and atrial fibrillation (AF) patients presented a significant higher expression of STAT3 and collagen in atria than wild-type mice and sinus rhythm subjects, respectively." (PMID 36743695, 2023). "Interestingly, in atrial fibrillation, FGF23 mediated profibrotic response via Stat3 and Smad pathways in cardiac fibroblasts, and CEBP-β was significantly upregulated in myocardial tissue of patients on dialysis, which showed enhanced LVH and LV fibrosis." (PMID 31540546, 2019).
autoimmune thyroiditis (7 papers, 2018 to 2025). "Total glucosides of paeony (TGP) can regulate the expression of SOCS1 in rats with autoimmune thyroiditis, enhance the expression of JAK1, JAK2, STAT3, and STAT5, thereby affecting the JAK/STAT signaling pathway." (PMID 40584613, 2025).
bone tumor (7 papers, 2014 to 2025). "This study underscores the potential carcinogenic effects of ATBC in bone cancer, identifying key targets such as STAT3, EGFR, MMP9, MAPK1, and MMP2." (PMID 40625361, 2025). "The centrality of STAT3 within the interaction network underscores its pivotal role in linking ATBC exposure to the pathogenesis of bone cancer." (PMID 40625361, 2025). "We identified 73 overlapping genes between ATBC exposure and bone cancer, subsequently prioritizing STAT3, EGFR, MMP9, MAPK1, and MMP2 as core targets." (PMID 40625361, 2025). "Accumulating evidence has revealed that pterostilbene and resveratrol can induce cell cycle arrest and apoptosis by inhibiting the upstream kinase activities of STAT3 signaling in several cancers such as breast, pancreatic, prostate, and bone tumors." (PMID 31935877, 2020). "Recent studies have suggested that the JAK2/STAT3 pathway is abnormally activated in different forms of chronic pain, including neuropathic pain, inflammatory pain, morphine tolerance and bone cancer pain." (PMID 37307838, 2024). "Altogether, these findings suggest that the clearance of apoptotic cancer cells by BM macrophages triggers p-STAT3/HIF-1α/MIF signaling to promote further inflammation in the bone tumor microenvironment where a significant number of apoptotic cancer cells are present." (PMID 36496973, 2022). "In addition, we demonstrated that Chi3L1 expression was correlated with p-STAT3 level in human bone tumor tissues." (PMID 31929760, 2020). "Furthermore, the anti-tumor effects of G721-0282 were observed in an xenograft in vivo model in association with the reduced expression of Chi3L1, PCNA, Cyclin D1, p-STAT3, as well as the increased expression of Chi3L1 was correlated with the p-STAT3 level in human bone tumor tissues." (PMID 31929760, 2020). "Notably, among these core targets, STAT3, EGFR, MMP9, MAPK1, and MMP2 were identified as the top five targets based on MCC values, serving as the hub targets of ATBC-induced bone cancer." (PMID 40625361, 2025). "Altogether, these results suggest that STAT3–HIF-1α–MIF is a potent signaling axis induced by BM macrophage efferocytosis of apoptotic cancer cells, which may act via paracrine signaling to induce macrophage-mediated inflammation in the bone tumor milieu." (PMID 36496973, 2022).
cervical disease (7 papers, 2010 to 2022). "Our immunoblotting, IHC and DNA binding assays revealed that aberrant STAT3 activity increases as a function of severity of the disease from precancer to cancer during cervical carcinogenesis and was found associated with HPV16 positive lesions." (PMID 20977777, 2010). "Finally, we demonstrate that STAT3 phosphorylation is increased during cervical disease progression, highlighting the potential of STAT3 as a novel therapeutic target in HPV-associated cancers." (PMID 29630659, 2018). "We previously demonstrated increased STAT3 phosphorylation in cervical disease and we now demonstrate a similar link between IL-6 levels and cervical disease." (PMID 31226168, 2019). "Increased STAT3 protein expression and phosphorylation also correlated with cervical disease progression in a panel of cytology samples." (PMID 31226168, 2019). "We revealed that STAT3 activation correlates with cervical disease progression." (PMID 31226168, 2019). "Finally, increased STAT3 expression and phosphorylation is observed in HPV positive cervical disease biopsies compared to control samples, highlighting a role for STAT3 activation in cervical carcinogenesis." (PMID 29630659, 2018). "A recent study has suggested that STAT3 is involved in HPV-16-induced cervical carcinogenesis." (PMID 27824155, 2016). "Signal transducer and activator of transcription 3 (STAT3) is an important regulator in malignant tumor, which also plays an essential role in the HPV positive cervical disease." (PMID 35057825, 2022). "The data shows that JAK2, STAT3 and STAT5 phosphorylation correlates with cervical disease progression." (PMID 31817106, 2019). "Together, these findings demonstrate that STAT3 phosphorylation is increased in HPV positive keratinocytes including those of a natural HPV infection and correlate with cervical disease progression." (PMID 29630659, 2018). "To look at the correlation of JAK2, STAT3 and STAT5 phosphorylation in cervical disease, we plotted the normalized intensities of phosphorylated JAK2 against that of phosphorylated STAT3 and phosphorylated STAT5 from CIN 3, which represents pre-cancerous lesions." (PMID 31817106, 2019). "Finally, we demonstrate that phosphorylation is essential for STAT3 function in the HPV replication cycle and is frequently increased in HPV-positive cervical disease." (PMID 29630659, 2018).
co-infection (7 papers, 2021 to 2025). "It has been reported that in an in vivo model of chemically induced carcinogenesis, the chronic co-infection of P. gingivalis and F. nucleatum activated the IL-6/STAT3 axis in the tongue epithelium, which in turn led to augmented tumor size and invasiveness." (PMID 38612423, 2024). "An even more significant increase in the phosphorylation level of STAT1 and STAT3 was detected in the co-infection group compared to any other group." (PMID 33968006, 2021). "Distinctly, VL1 patient, that has disorganized spleen and VL-HIV coinfection was related to SOD1, STAT3, STAT4, ICOS, TRAF6 and IRF3 genes, and CD8+ cells in the RP and expression of IL6 in both regions of spleen." (PMID 38843306, 2024). "The phosphorylation level of STAT1 and STAT3 was significantly increased after H9N2 and E. coli co-infection." (PMID 33968006, 2021). "Therefore, we analyzed the differential expression of STAT family genes and found that HIV-mono infection leads to the upregulation of STAT3 and STAT4, whereas co-infection results in the upregulation of STAT1 and STAT2." (PMID 41394852, 2025). "Only some co-infection conditions resulted in fully activated STAT-1 and phosphorylated STAT-3." (PMID 36389843, 2022). "Nonetheless, persistent STAT3 activation and further upregulation of STAT4 — a key regulator of Th1 differentiation — could exacerbate chronic inflammation and tissue damage in co-infection." (PMID 41394852, 2025). "Moreover, we found that IL-6 and TNF-α, generally induced by LPS, may promote BTLA expression on CD4+ T cells via the STAT3 and NF-κB signaling, which explains why HBV-ACLF patients with coinfection have elevated BTLA levels." (PMID 38418488, 2024).
cystic kidneys (7 papers, 2016 to 2025). "Initially, individual antibodies (anti-CD163 or anti-phospho-STAT3) were used for immunohistochemical staining of adjacent serial sections of ADPKD cystic kidneys to look for interstitial phospho-STAT3-positive cells, specifically in macrophage-rich areas." (PMID 27491076, 2016). "Given the demonstration here of activated STAT3 in renal macrophages of ADPKD cystic kidneys, we think it likely that the unidentified phospho-STAT3-positive interstitial cells in the cystic kidneys noted in all those previous studies were macrophages." (PMID 27491076, 2016). "Here, we have demonstrated colocalization of activated STAT3 and a marker of M2-like macrophages in human ADPKD cystic kidneys, suggesting that the macrophage IL-10–STAT3 pathway is induced during macrophage programming in human disease." (PMID 27491076, 2016). "In those studies, activated STAT3 strongly correlates with the cystic kidney phenotype in both human ADPKD and multiple mouse models of PKD." (PMID 27491076, 2016). "This is the first study that reveals that abnormal expression of xFOSL1 caused the formation of dilated pronephric tubule, resembling renal cyst observed in JSRD, downstream of IL-6/JAK/STAT3 signaling." (PMID 40570958, 2025). "STAT3 and RUNX1 displayed the strongest activation in cystic kidneys, as demonstrated by chromatin immunoprecipitation (ChIP) followed by qPCR." (PMID 31773180, 2019). "For two of the identified TFs, STAT3 and RUNX1, we also showed increased activity in mouse cystic kidneys, as well as altered expression in human ADPKD kidneys." (PMID 31773180, 2019). "By performing ChIP-qPCR for STAT3 and RUNX1 in ADPKD-affected kidneys, we confirmed increased transcriptional activity in cystic kidneys for these TFs." (PMID 31773180, 2019). "Sections of ADPKD cystic kidneys were also prepared for immunofluorescence co-staining for CD163 and phospho-STAT3." (PMID 27491076, 2016). "We then investigated whether binding of STAT3 and RUNX1 at the promoter region of their target genes is increased in cystic kidneys compared to non-cystic kidneys." (PMID 31773180, 2019). "While, during the progression of ADPKD, the cleaved PC1 tail could co-activate STAT1 that had been activated by IFN, STAT3 that had been activated by IL-6, EGF, HGF (hepatocyte growth factor) signaling, STAT6 that had been activated by IL4, IL-13 signaling to promote renal cyst growth and fibrosis." (PMID 34199002, 2021). "Genetic knockout of STAT3 and STAT6, STAT3 inhibitor S3I-201, STAT6 non-specific inhibitor teriflunomidelysine, methyltransferase SMYD2 specific inhibitor AZ505, or anti-parasitic compound pyrimethamine could attenuate ADPKD cell proliferation and reduce renal cyst formation." (PMID 34199002, 2021).
Duchenne muscular dystrophy (7 papers, 2018 to 2024). Duchenne muscular dystrophy (DMD) is a neuromuscular disease characterized by rapidly progressive muscle weakness and wasting due to degeneration of skeletal, smooth and cardiac muscle. "STAT3 signaling has been shown to be activated in skeletal muscle and promotes skeletal muscle atrophy in muscle diseases, such as Duchenne muscular dystrophy (DMD), and Merosin-deficient congenital muscular dystrophy (MDC1A), as well as cancer and sepsis." (PMID 30072615, 2018). "Treatment in the Duchenne muscular dystrophy mouse model with these IL6ST decoy receptor EVs resulted in a reduced phosphorylation of STAT3 in muscles; further functional studies verified the in vivo activity of the decoy receptor EVs as a potential therapy." (PMID 33579329, 2021). "In studies using muscle cells and a mouse model of Duchenne muscular dystrophy (DMD), IL6ST DR EVs successfully inhibited the activation of STAT3, a protein involved in inflammation and muscle degeneration." (PMID 39184952, 2024). "Activation of the STAT3 pathway has been shown to induce muscle tissue atrophy in Duchenne muscular dystrophy (DMD), Merosin-negative congenital muscular dystrophy (MDC1A), sepsis, and in the vast majority of cancers." (PMID 33158194, 2020).